CDK3 (cyclin dependent kinase 3)
Description:
Serine/threonine-protein kinase that plays a critical role in the control of the eukaryotic cell cycle; involved in G0-G1 and G1-S cell cycle transitions. Interacts with CCNC/cyclin-C during interphase. Phosphorylates histone H1, ATF1, RB1 and CABLES1. ATF1 phosphorylation triggers ATF1 transactivation and transcriptional activities, and promotes cell proliferation and transformation. CDK3/cyclin-C mediated RB1 phosphorylation is required for G0-G1 transition. Promotes G1-S transition probably by contributing to the activation of E2F1, E2F2 and E2F3 in a RB1-independent manner.
Tractability: Small molecule: a drug acting on it is in phase 2 or 3 trials; a structure with a bound ligand is known; a high-quality ligand is known; it belongs to a druggable protein family. PROTAC: ubiquitination databases record sites on it; its protein half-life has been measured; a small molecule that binds it is known.
Target class: CMGC protein kinase CDC2 subfamily; Kinase; CMGC protein kinase CDK family; CMGC protein kinase group; Enzyme; Protein Kinase
Gene: Protein-coding gene on chromosome 17 (76,000,644 to 76,005,999, forward strand). Ensembl gene ENSG00000250506.
Subcellular location (Human Protein Atlas): Cytosol
Gene Ontology:
Molecular function: protein binding; cyclin-dependent protein serine/threonine kinase activity; ATP binding; protein kinase activity; protein serine kinase activity
Biological process: DNA damage response; G0 to G1 transition; negative regulation of Notch signaling pathway; cell population proliferation; G1/S transition of mitotic cell cycle; G2/M transition of mitotic cell cycle; regulation of cell cycle
Cellular component: cyclin-dependent protein kinase holoenzyme complex
Genetic constraint (gnomAD): Loss-of-function variants: 22 observed, 29.04 expected, observed/expected ratio (o/e) 0.76, 90% interval 0.54 to 1.08. The upper end of that interval is the gene's LOEUF score, 1.08, which puts it in group 4 of 6, group 1 being the genes least tolerant of losing a copy. Missense variants: 310 observed, 356.6 expected, observed/expected ratio (o/e) 0.87, 90% interval 0.79 to 0.95. Synonymous variants: 144 observed, 149.43 expected, observed/expected ratio (o/e) 0.96, 90% interval 0.84 to 1.11.
Homologues: Orthologues: chimpanzee CDK3 (99% identical), macaque CDK3 (97% identical), dog CDK3 (91% identical), pig CDK3 (90% identical), rabbit CDK3 (89% identical), mouse Cdk3 (82% identical), Drosophila melanogaster Cdk2 (61% identical). Paralogues in human: CDK2 (74% identical), CDK1 (63% identical), CDK5 (59% identical), CDK14 (51% identical), CDK16 (51% identical), CDK17 (51% identical), CDK18 (50% identical), CDK15 (49% identical), CDK6 (46% identical), CDK11B (45% identical), CDK11A (45% identical), CDK7 (45% identical), and 14 more.
Diseases named in the same sentence as CDK3 in open-access papers:
CDK3 is named in the same sentence as 35 diseases in open-access papers, as found by Europe PMC text mining. Sharing a sentence is not in itself a finding about the gene and the disease. The quoted sentences say what the papers report.
breast cancer (13 papers, 2015 to 2025). A primary or metastatic malignant neoplasm involving the breast. "Expression assays in breast cancer samples have shown that up-regulation of CDK3 is associated with chemoresistance." (PMID 36266723, 2022). "An interesting observation that might merit to be confirmed is the association of CDK3 overexpression due to gene rearrangements with BRCA1 loss of heterozygosity (LOH) in breast cancer, a tumor in which CDK3 activity has been linked to tamoxifen resistance." (PMID 39800748, 2025). "Cyclin-dependent kinase 3 (CDK3), that has been identified as a specific target of miR-873, is overexpressed in breast cancer." (PMID 38428865, 2024). "The CDK3 targeting miRNA, miR‐125a‐3p has also been revealed to inhibit transactivation of ERα and prevail tamoxifen resistance in ER + breast cancer cells." (PMID 36266723, 2022). "HuR can directly bind to and regulate the expression of CDK3 mRNA, thereby promoting the progression of breast cancer." (PMID 36059653, 2022). "Cyclin-dependent kinase 3 is also overexpressed in various tumor tissues, such as breast cancer and nasopharyngeal carcinoma." (PMID 35814446, 2022). "For instance, overexpression of CDK3 can suppress the migration and invasion of breast cancer cells." (PMID 35814446, 2022). "It is first identified to suppress breast cancer cell proliferation and enhance tamoxifen resistance by targeting CDK3." (PMID 31289617, 2019). "Our data shows that NCTD regulates ERα signaling and tamoxifen resistance by targeting miR-873/CDK3 axis in breast cancer cells." (PMID 31120927, 2019). "In this study, we have demonstrated the role of NCTD in regulating ER signaling and tamoxifen resistance of human breast cancer cells via miR-83/CDK3 axis." (PMID 31120927, 2019). "Here we report that Norcantharidin (NCTD), currently used clinically as an ani-cancer drug in China, regulates miR-873/CDK3 axis in breast cancer cells." (PMID 31120927, 2019). "Taken together, our data shows that NCTD overcomes tamoxifen resistance by targeting miR-873/CDK3 axis in breast cancer cells." (PMID 31120927, 2019). "To investigate the potential role of CDK3 in breast cancer, we first examined CDK3 expression in different breast cancer cell lines." (PMID 29156693, 2017). "In our study, we compared CDK3 expression in normal breast tissue and breast cancer tissue by using a tissue microarray." (PMID 29156693, 2017). "In conclusion, our data identified CDK3 as a suppressor of metastasis in breast cancer and indicated that Wnt/β-catenin signaling was the potential downstream of CDK3." (PMID 29156693, 2017). "Taken together, these data suggested that CDK3, which is targeted by miR-4469, plays an inhibitory role in breast cancer metastasis by inhibiting Wnt/β-catenin pathway." (PMID 29156693, 2017). "As determined by total body luminescence, MDA-MB-231-luci-CDK3-wt exhibited a dramatic inhibition of experimental metastasis compared to the control cells, supporting the suppressive role of CDK3 in breast cancer metastasis." (PMID 29156693, 2017). "To further investigate the role of CDK3 in breast cancer metastasis, we infected malignant breast cancer cell line MDA-MB-231 and BT549 cells with lentivirus-expressing wild-type CDK3." (PMID 29156693, 2017). "To elucidate the mechanism of suppression of cell motility and metastasis by CDK3 in breast cancer, we examined the mRNA expression profile in both CDK3-overexpressed MDA-MB-231 or BT549 cells, and CDK3-silenced MCF7 cells." (PMID 29156693, 2017). "Overexpression of CDK3 suppressed cell migration and invasion of breast cancer cells, and decreased the metastasis in nude mice." (PMID 29156693, 2017). "In conclusion, these results support that CDK3 which is targeted by miR-4469 suppresses breast cancer metastasis by inhibiting Wnt/β-catenin pathway." (PMID 29156693, 2017). "It is strongly providing the evidence that CDK3 exerts the inhibitory role in breast cancer motility by inhibiting Wnt/β-catenin pathway." (PMID 29156693, 2017).
breast cancer (continued). "Similarly, miR-873 has been found to regulate transcriptional activity of ERα and resistance to tamoxifen through influencing expression of CDK3 in breast cancer cells." (PMID 36266723, 2022). "In addition, HuR and CDK3 expression levels were positively correlated and significantly up-regulated in breast cancer samples." (PMID 36059653, 2022). "Up-regulation of CDK3 in breast cancer cells has suppressed their migration and invasion." (PMID 36266723, 2022). "While a single study in breast cancer models has shown that up-regulation of CDK3 decreases metastatic abilities of breast cancer cells, other studies have shown that up-regulation of CDK3-targeting miRNAs miR-125a-3p and miR-873 leads to reduction of tumor growth." (PMID 36266723, 2022). "CDK3 is abnormally expressed in several types of cancer, including gastric cancer, lung cancer, liver cancer, pancreatic cancer, colorectal cancer, head and neck squamous cell carcinoma, cervical cancer and breast cancer." (PMID 33504681, 2021). "NCTD inhibits breast cancer cell growth in vitro and in vivo through regulating miR-873/CDK3 axis." (PMID 31120927, 2019). "Mir-873 exerted its functions through inhibiting CDK3 expression in breast cancer." (PMID 31120927, 2019). "CDK3 is the direct target of miR-873 and is overexpressed in breast cancer." (PMID 31120927, 2019). "In breast cancer and glioblastoma tissue, CDK3 is overexpressed." (PMID 31120927, 2019). "However, CDK3 overexpression dramatically decreased colony formation of MDA-MB-231 cells in 2-D culture dishes, suggesting that CDK3 is also related with clonogenic ability of breast cancer cells." (PMID 29156693, 2017). "Altogether, these findings demonstrate that CDK3 is the direct target of miR-4469 and miR-4469 could increase the motility of breast cancer cells through targeting CDK3." (PMID 29156693, 2017). "Moreover, the signaling pathway induced by CDK3 was estimated based on RNA-seq results among breast cancer cell lines altered the expression of CDK3." (PMID 29156693, 2017). "We found that CDK3 exhibited a lower level in normal breast tissues than breast cancer tissues." (PMID 29156693, 2017). "As shown here, CDK3 exhibited a potent inhibitory effect on Wnt signaling in breast cancer cells through regulating the phosphorylation level of LRP6, the expression of Axin1 and Dvl2, leading to the inhibition of β-catenin, and this process is possibly due to decreased expression of Wnt3a." (PMID 29156693, 2017). "In that study, they also demonstrated that CDK3 is required for breast cancer cell proliferation." (PMID 29156693, 2017). "However, in our study, overexpression of CDK3 exerts an inhibitory effect of breast cancer motility both in vitro and in vivo, which provides a novel role of CDK3 in cancer." (PMID 29156693, 2017). "Consistent with our hypothesis, the level of miR-4469 was abundant in malignant breast cancer cell lines, which is in contrary to the protein level of CDK3." (PMID 29156693, 2017). "Therefore, targeting miR-873/CDK3 could serve as a promising therapeutic strategy for combating tamoxifen resistance in breast cancer." (PMID 38428865, 2024). "Thus, targeting miR-873/CDK3 may be a potential therapeutic approach for the treatment of ER positive breast cancer especially tamoxifen resistant breast cancer." (PMID 31120927, 2019). "Then, we explored if miR-4469 could enhance breast cancer cell motility through targeting CDK3." (PMID 29156693, 2017). "In addition, we examined CDK3 expression by immunohistochemisty in normal breast tissue and breast cancer tissue by using a tissue microarray including 59 cases of normal breast tissues and 194 cases of breast cancer tissues." (PMID 29156693, 2017). "When CDK3 expression is repressed by miR-1205, SNAIL accumulates intracellularly to promote EMT and breast cancer metastases." (PMID 39736850, 2025).
breast cancer (continued). "CDK3 is a cyclin-dependent kinase, which can phosphorylate the estrogen receptor (ER) and enhance ER activity, thereby promoting the occurrence and development of breast cancer (BC)." (PMID 34676171, 2021). "For instance, miR-1205 could suppress the expression of cyclin-dependent kinase 3 (CDK3), a cellular protein that binds SNAIL to induce its degradation in breast cancer cells." (PMID 39736850, 2025). "Treatment of breast cancer cells with NCTD has led to reduction of transcriptional activity of ERα but not ERβ via influencing activity of miR-873/CDK3 axis." (PMID 36266723, 2022). "In this study, we demonstrated that CDK3 is highly expressed in primary tumors of non-metastatic breast cancer compared with those in metastatic breast cancer and CDK3 suppresses breast cancer metastasis." (PMID 29156693, 2017). "Here, we first found that the expression of CDK3 was higher in primary tumors of non-metastatic breast cancer compared with those in metastatic breast cancer." (PMID 29156693, 2017). "Thus, the function of CDK3 on cell proliferation should be further confirmed, especially between ER-positive and ER-negative (e.g. MDA-MB-231) breast cancer cell lines." (PMID 29156693, 2017). "According to the computational methods, miR-4469 was found as a negative regulator of CDK3 by directly targeting CDK3 3′UTR, and subsequent experiments suggested that the up-regulation of miR-4469 level could be responsible for the increase of breast cancer motility." (PMID 29156693, 2017). "The immunohistochemistry results revealed that CDK3 was highly expressed in primary tumor tissues of non-metastatic breast cancer, implying that CDK3 might be involved in breast cancer metastasis." (PMID 29156693, 2017).
colorectal cancer (7 papers, 2016 to 2023). A primary or metastatic malignant neoplasm that affects the colon or rectum. "The whole transcriptome sequencing showed that the increased expression of SLC27A2 can lead to the downregulation of CDK3, and it has been reported that CDK3 promotes the EMT process in colorectal cancer." (PMID 35927229, 2022). "In xenograft models of colorectal cancer, up-regulation of CDK3 has been accompanied by enhancement of metastatic ability of cancer cells." (PMID 36266723, 2022). "Colorectal cancer tissues showed enhanced expression levels of CDKs 1/2/4/5/6/8/12/13/19 but reduced CDK3 expression." (PMID 35814446, 2022). "In colorectal cancer cells, Cdk3 has been shown to promote epithelial-mesenchymal transition (EMT) via enhancing activity of AP-1." (PMID 36266723, 2022). "Higher expression of CDK3 was reported in other cancers, such as glioblastoma, skin cancer and colorectal cancer." (PMID 29156693, 2017). "Further, Cdk3 expression-vector was used to investigate its effect in cancer metastasis, we found that Cdk3 can promote the motility and invasion of colorectal cancer cell in vitro and metastasis ex vivo, mediate cell EMT shift." (PMID 26755651, 2016). "It was confirmed that Cdk3 ectopic expression increases cell motility and invasion in vitro, enhances colorectal cancer metastasis ex vivo." (PMID 26755651, 2016). "Herein, we found that Cdk3 increased colorectal cancer metastasis through promoting epithelial-mesenchymal transition (EMT) shift." (PMID 26755651, 2016). "Ectopic expression of Cdk3 promoted colorectal cancer from epithelial to mesenchymal transition conjugating AP-1 activation, while AP-1 inhibition dramatically decreased Cdk3-increased EMT shift." (PMID 26755651, 2016). "Our analysis indicated that CDK3 is actually downregulated in colorectal cancer tissues, which could enhance migration and invasive capacities." (PMID 35814446, 2022). "Additionally, Cdk3 was also found to induce colorectal cancer cell from epithelial to mesenchymal transition through activating AP-1." (PMID 26755651, 2016). "Additionally, the correlation of CDK3 expression with clinical features and prognosis of colorectal cancer patients was analyzed, Cdk3 expression is related with TNM grade (P < 0.05)." (PMID 26755651, 2016). "To confirm this speculation, we at first detected Cdk3 protein expression and activity in the biopsy tissues of colorectal cancer, and found that both Cdk3 expression and activity are high in metastatic tissues." (PMID 26755651, 2016). "The results suggested that Cdk3 plays an important role in hepatic metastases of colorectal cancer." (PMID 26755651, 2016). "Since the enhanced migratory/invasive ability of epithelial cells is often caused by EMT, we analyzed a panel of representative epithelial and mesenchymal markers to determine whether this process occurs in Cdk3 mediating colorectal cancer metastasis." (PMID 26755651, 2016). "To further analyze the mechanism of Cdk3-mediated metastasis, based on the previous finding, Cdk3 activating AP-1 through phosphorylating c-Jun, we investigated whether Cdk3-activating AP-1 participates in colorectal cancer metastasis." (PMID 26755651, 2016). "We think that Cdk3 may also promote colorectal cancer metastasis through regulating EMT shift." (PMID 26755651, 2016). "Taken together, our data indicated that Cdk3 activates AP-1through phosphorylating c-Jun Ser 63/73, induces EMT alteration, increases motility and invasion of colorectal cancer, and finally promotes colorectal cancer invasion and migration." (PMID 26755651, 2016). "We speculated that Cdk3 may mediate AP-1 activation, promote EMT shift, and promote colorectal cancer metastasis." (PMID 26755651, 2016). "To further investigate whether endogenous Cdk3 contributes to EMT phenomenon, we observed whether colorectal cancer cells lacking endogenous Cdk3 expression demonstrate any EMT-like cellular marker reversal." (PMID 26755651, 2016).
lung carcinoma (7 papers, 2008 to 2024). "A potential interplay between HuR, miR-873 and miR-125a-3p has also been suggested for the regulation of cancer stemness through the regulation of CDK3 (Cyclin Dependent Kinase 3) expression in lung cancer." (PMID 35884580, 2022). "During the preparation of this manuscript, miR-873/CDK3 has been shown to function in cancer stemness of lung cancer cells." (PMID 31120927, 2019). "HuR promotes lung cancer by opposing miR-873 and miR-125a-3p, competitively binding to CDK3 mRNA." (PMID 34998399, 2022). "To further verify the role of NDUFA4 in the growth and metastasis of lung cancer cells, we detected the expression of cell-growth-related molecules including CDK2, CDK3, CDK4, and CDK6, as well as metastasis-related molecules including CXCR4, E-Cadherin, MMP2, MMP3, and MMP9, respectively." (PMID 28325285, 2017).
colon cancer (3 papers, 2016 to 2023). "In colon cancer, nasopharyngeal cancer and other tumor tissues, CDK3 had been found to have an unusually high expression rate, playing an important role in cell proliferation and malignant carcinogenesis." (PMID 37198697, 2023). "This suggests that Cdk3 expression may be related to colon cancer progression." (PMID 26755651, 2016).
prostate carcinoma (2 papers, 2015 to 2023). A carcinoma that arises from epithelial cells of the prostate gland. "Simvastatin and lovastatin suppressed expression of CDK1, CDK2, CDK3, CDK4, and CDK6 in prostate cancer cells with reduced cell viability due to induced apoptosis and cell cycle arrest." (PMID 36946734, 2023). "In LNCaP prostate cancer cells, reduced expression of SAM68 altered the expression of an important subset of genes involved in proliferation and apoptosis, including Bcl2L1, Clusterin, cdk2, cdk3, p16INK4, cyclin D1, Par-4, EGF and IGF-1." (PMID 25944080, 2015).
skin cancer (2 papers, 2017 to 2022). "Of note, both CDK3 and NFATc4 are highly expressed among various types of skin tumor tissues compared with normal tissues." (PMID 35698138, 2022). "Further study elucidated that CDK3 phosphorylated NFATc4 at Ser259 and enhanced NFATc4 effect on skin cancer, and EGF treatment could promote CDK3/NFATc4-mediated cell transformation and proliferation." (PMID 35698138, 2022). "Moreover, CDK3 increases AP-1 transactivation resulted in an increase of Ras-induced transformation in NIH3T3 cells, and promotes skin cancer cell growth via elevating the phosphorylation level of its binding transcriptional factor NFAT3." (PMID 29156693, 2017).
carcinoid tumor (1 paper, 2016). A slow growing neuroendocrine tumor, composed of uniform, round, or polygonal cells having monotonous, centrally located nuclei and small nucleoli, infrequent mitoses, and no necrosis. "In addition, IFN-α inhibited cyclin dependent kinases (CDK), CDK2-, CDK3-, CDK4-, and cyclin E- but not cyclin A-associated kinase activities and induced cell cycle arrest in carcinoid tumor." (PMID 26993600, 2016).
hepatitis B (1 paper, 2016). "Next, using the DIANA-mirPath program, we investigated the mechanism by which miR-214/199a/199a* activates hepatitis B signaling, pathways in cancer and cell cycle, and found that 3 central cell-cycle promoting genes, E2F2, CDK3 and CDK6 was strikingly enriched in these predicted targets pathway." (PMID 26498144, 2016).